MMP2 (matrix metallopeptidase 2)
Diseases named in the same sentence as MMP2 in open-access papers (continued):
Sharing a sentence is not in itself a finding about the gene and the disease.
melanoma (continued). "CREB (cAMP response element-binding protein) and its associated proteins (e.g., MMP-2, MCAM and MUC18) play a key role in tumor growth and metastasis of human melanomas." (PMID 29377892, 2018). "As already reported in fibrosarcoma 36, melanoma 38 and lung carcinoma 9, we observed that EDPs promoted MMP‐2 secretion and activation in MDA‐MB‐231 cells." (PMID 30186741, 2018). "IPA analyses of transcriptomic expression profiles indicated TNF, the MMP-2 and IL-6 pathways as the most significantly upstream regulators, strongly suggesting them as possible key modulators of the melanoma cell aggressiveness." (PMID 30591049, 2018). "Recently, DATS was shown to inhibit human melanoma cell migration and invasion by reducing the expression of matrix metalloproteinase-2 (MMP-2) and MMP-9, as well as inhibiting adhesion by disrupting the integrin signal pathways." (PMID 29565284, 2018). "Among human melanoma cells, MMP-2 and MMP-9 have attracted attention in the recent years, especially with regard to cutaneous, eye, and oral melanomas." (PMID 29492694, 2018). "MMP-2 has been shown to enhance adhesion and migration of melanoma cells via increasing cleavage of fibronectin, and MMP-9 overexpression has been found to be associated with tumor melanoma invasion and migration." (PMID 30042328, 2018). "The results indicated that regulation of MMP-2/-9-related signaling pathways is involved in the process of human melanoma cell metastasis." (PMID 30042328, 2018). "In a different setting, an outside-in integrin-signaling was required for exocytosis of MMP-2 by human melanoma cells." (PMID 29849044, 2018). "Zymography used to measure the activity of metalloproteinases in melanoma cells revealed a significant difference between MMP-2 and MMP-9 activities in N-cadherin knocked-down cells in all tested cell lines in comparison with untreated ones." (PMID 29492694, 2018). "Effects of MMP2 on downstream transcripts differentially expressed in A357 vs SK-MEL-28 human melanoma cells." (PMID 30591049, 2018). "For these purposes, we performed the MMP-2 activation assay using murine melanoma B16F1 cells with the enforced expression of murine MT1-MMP (B16F1-mMT1 cells)." (PMID 27835863, 2017). "It is known that CREB induces metastasis of melanoma via MMP2 and adhesion molecules such as MCAM/MUC18 and dominant-negative mutant CREB has been shown to suppress metastasis." (PMID 29285247, 2017). "Relative to the melanoma cells, in this case pretreatment with extract also significantly decreased the levels of IL-8, IL-6, MMP-2 and MMP-9." (PMID 28264501, 2017). "In vivo it also downregulates MMP-2 in a human melanoma mouse model, and MMPs-2 and -14 in gallbladder cancer, thereby enhancing the VM-inhibiting activity of TIMP-2." (PMID 29112161, 2017). "LKB1 expression level inversely correlated with MMP-2 expression level in melanoma tissues in the presence of BRAF V600E." (PMID 29371951, 2017). "In conclusion, Rictor plays an important role in melanoma VM via the Rictor—AKT—MMP‐2/9 signalling pathway." (PMID 28699701, 2017). "In summary, our results demonstrated that LKB1 inactivation plays a cooperative role with BRAF mutation in promoting melanoma cells invasion and migration by activation of PI3K/Akt/mTOR signaling pathway and MMP-2 expression." (PMID 29371951, 2017). "The combined effects of decline in ARSB on the increased expression of CSPG4 proteoglycan and of pro-MMP2 contribute to the increased invasiveness of melanoma cells." (PMID 27926479, 2017). "We also retrospectively tested the LKB1 and MMP-2 expression using immunohistochemistry in formalin fixed paraffin embedding (FFPE) tissues from patients with melanoma." (PMID 29371951, 2017).
melanoma (continued). "Unexpectedly, we found that LKB1 inactivation synergism with BRAF V600E significantly promotes melanoma cells invasion and migration by expression of MMP-2." (PMID 29371951, 2017). "Our findings implicating that regulation of CREB in the MMP-2 are consistent with those of previous studies on melanomas and ovarian cancer." (PMID 29285298, 2017). "PB was found effective in inhibition of fibrosarcoma HT-1080 and melanoma A2058 cell proliferation, MMP-2 and -9 expression, invasion through Matrigel and inducing apoptosis, important parameters for cancer prevention." (PMID 27618095, 2016). "In the present study we show that CoQ0 treatment significantly inhibits melanoma migration and invasion by down-regulating MMP-2, MMP-9 and up-regulating TIMP-1 and TIMP-2 expressions." (PMID 26968952, 2016). "In particular, MMP-2 overexpression has been correlated with tumor progression and poor survival in melanoma patients." (PMID 26517521, 2016). "Melanoma cells were more sensitive to PB, as their proliferation was inhibited by 80% at 25 ug/mL and MMP-2 and -9 secretion and Matrigel cell invasion blocked completely at 50 μg/mL, indicating strong anti-invasive properties of this polyphenol mixture." (PMID 27618095, 2016). "Over expressions of MMPs including MMP-9 and MMP-2 plays a pivotal role in melanoma migration and invasion by stimulating degradation of the extracellular matrix." (PMID 26968952, 2016). "The administration of recombinant gC1qR induces cell migration via integrin- and NFκB-dependent matrix metalloprotease-2 (MMP-2) activation in B16F10 mouse melanoma cells." (PMID 27363031, 2016). "MALAT1 can promote the growth and metastasis of melanoma cells though sponging miR-22, functionally releasing MMP14 and Snail mRNA transcripts targeted by miR-22, causing MMP2 activation and E-cadherin down-regulation, and inducing ECM remodelling and EMT." (PMID 27564100, 2016). "Its observed effect on MMP-2, can be of particular relevance in the context of melanoma, notorious for its highly aggressive and angiogenic nature, with ten-year survival rates as low as 10-15% in cases of advanced stage tumors." (PMID 27014725, 2016). "Secretion of MMP-2 by melanoma cells was significantly inhibited by zeaxanthin in a dose-dependent manner as measured by ELISA kit." (PMID 26942004, 2016). "In this regard, it is plausible to postulate that apigenin inhibited melanoma invasiveness by decreasing MMP-2 activity and expression through suppressing the constitutively active STAT3." (PMID 26911838, 2016). "In two previous studies, we showed that JWA inhibited oncogenic transcript factor Sp1, which in turn inhibited the MMP-2-dependent angiogenic potential of endothelial cells in gastric cancer and integrins αV and β3 in melanoma metastasis." (PMID 27167206, 2016). "Brain-metastasizing melanoma cells stimulate astrocytes to express the pro-inflammatory IL-23 cytokine resulting in IL-23-mediated stimulation of melanoma cells to secrete matrix metalloproteinase 2 (MMP2)." (PMID 27598148, 2016). "It has also been shown that CD146 contributes to human melanoma cell invasion through the regulation of MMP-2 transcription and protein expression via Id-1." (PMID 25685061, 2015). "Recent studies have also shown that MMP2 is inversely correlated with the survival of patients with melanoma." (PMID 25954957, 2015). "GLUT1 suppressed melanoma cells revealed significantly reduced proliferation, apoptosis resistance, migratory activity and matrix metalloproteinase 2 (MMP2) expression." (PMID 26293674, 2015). "We examined MMP-13–Ln-5 cleavage fragments to explore their mechanism for increased invasiveness in melanoma, and compared them with MMP-2–Ln-5 γ2 cleavage products, which reportedly also induce tumor cell invasiveness." (PMID 25749207, 2015). "Mechanistically, we find that MT1-MMP downregulates SPRY4 expression trough an MMP2/RAC1 axis we previously showed promotes melanoma cell motility downstream of MT1-MMP." (PMID 26392417, 2015).
melanoma (continued). "In particular, mmp2 is crucial for melanoma invasion and its expression level correlates directly with the pathogenesis of melanoma." (PMID 25671570, 2015). "The resulting decrease in PTEN protein was associated with enhanced expression of MMP-2 and MMP-9, two matrix proteases that are also implicated in melanoma pathogenesis." (PMID 25587717, 2015). "The results showed that in 365 melanoma samples, melanomas with high NRP1 expression also exhibited a significantly higher percentage of high MMP2 staining." (PMID 25954957, 2015). "Treatment of four different human melanoma cell lines with a pharmacological GLUT1 inhibitor caused a dose-dependent reduction of proliferation, apoptosis resistance, migratory activity and MMP2 expression." (PMID 26293674, 2015). "We have previously shown that MT1-MMP mediated melanoma cell migration depends on the activation of an MMP2/RAC1 signaling axis." (PMID 26392417, 2015). "Our findings implicating CREB phosphorylation in the regulation of MMP-2 in osteosarcomas are consistent with those in reports on melanomas and ovarian cancer." (PMID 25605016, 2015). "In general, MMP2 is secreted in latent form and is activated on the cell surface; integrins localize active MMP2 on the surface of invasive melanoma cells." (PMID 26329521, 2015). "After LIFr knockdown, the active MMP2 consolidated from melanoma cell conditioned medium was reduced, indicating that LIFr helps activate MMP2." (PMID 26329521, 2015). "Published data suggests that CAV1 can be an important regulator of the expression and activity of MMPs, including CAV1 unregulated MMP-2 and 9 in melanoma cells." (PMID 25180681, 2014). "Recent work by Godefroy and colleagues showed that MMP-2 in melanoma degrades type I IFN receptor, effectively preventing IL-12p35 production, and skews CD4 T cells towards a Th2 phenotype." (PMID 25491880, 2014). "The developed nanoparticles containing LHRH and MMP2 peptides showed preferential accumulation in primary and metastatic tumors increasing the MRI signal in mice with melanoma, lung and ovarian cancers." (PMID 24919932, 2014). "The results suggest that ALDOA is a critical mediator of the promoting effect of ANGPTL4 on melanoma cell invasion, likely through upregulating the MMP-2 expression." (PMID 24959248, 2014). "CD147 regulates calcium signaling and hypoxia-induced MMP-2 activities via interacting with calcium-modulating cyclophilin ligand for human melanoma progression." (PMID 25268615, 2014). "We show that WNT5A signaling induces a Ca2+-dependent release of exosomes containing the immunomodulatory and pro-angiogenic proteins IL-6, VEGF and MMP2 in melanoma cells." (PMID 24766647, 2014). "MMP2/ab733 Mn3O4 NPs were also used as the contrast agents for the detection of melanoma in transgenic mice." (PMID 24919932, 2014). "The primary melanoma line WM793 secreted only small amounts of a gelatinase (presumably metalloprotease-2) (MMP-2)." (PMID 24905466, 2014). "Manganese oxide nanoparticles (Mn3O4 NPs) were synthesized and modified with LHRH targeting peptide or anti-melanoma antibodies (cancer targeting moieties) and a MMP2 cleavable peptide (a possible chemotactic factor)." (PMID 24919932, 2014). "Expression of IL-8 by human melanoma cells up-regulates MMP-2 activity to increase tumor growth and metastasis." (PMID 23349885, 2013). "Similar conclusions were drawn from a study by Tekle and his colleagues, which proved that B7-H3 contributed to the metastatic capacity of melanoma cells by modulation of MMP-2 and signal transducer and activator of transcription 3 (Stat3)." (PMID 23940627, 2013). "Collectively, the data suggest that CSPG4 acts as a scaffold at the cell membrane to facilitate the formation of molecular complexes that stabilize integrins and receptor tyrosine kinases, and localize active MMP-2 to the melanoma cell surface." (PMID 24069584, 2013).
melanoma (continued). "A previous study found that the invasive ability of melanoma cells was positively correlated with the level of MMP-2 and that SPARC can induce invasive breast cells to produce MMP-2." (PMID 23516489, 2013). "The role of αvβ3 in MMP-2 activation seems to be most important in the invasive growth phase of melanoma as expression of this integrin begins when melanoma cells switch from a horizontal to a vertical growth phase." (PMID 24069584, 2013). "MCAM, CSPG4, and Gal-3 are associated with angiogenesis and CSPG4 is involved with the activation of pro-MMP-2 on melanoma (relevant references are in the review)." (PMID 24069584, 2013). "In another study of biopsies from patients with primary melanoma and patients with cutaneous or nodal metastases, MMP-2 expression was primarily in thick primary melanoma and in melanomas from patients who developed metastasis in the 3-year follow-up period." (PMID 24069584, 2013). "The proteolytically activated form of the C terminus of MMP-2 can bind integrins on melanoma cells and blood vessels." (PMID 23304519, 2012). "MMP-2 is strongly expressed in malignant melanomas and it correlates with invasion and metastatic behavior." (PMID 22929570, 2012). "Previous in vitro studies have shown that NM significantly inhibited melanoma and other cancer cell MMP-2 and -9 secretion and Matrigel invasion." (PMID 23226724, 2012). "Earlier studies have shown that the overexpression of MCAM in melanoma increased the expression of matrix metalloproteinase-2 (MMP-2), thereby contributing to the degradation of the extracellular matrix by tumour cells and promoting metastasis." (PMID 22610942, 2012). "The results demonstrated that MMP-2 activity was essential for αvβ3 integrin-dependent adhesion of human melanoma cells." (PMID 22848537, 2012). "Forced expression of MCAM in MCAM-negative melanoma cells led to a significant increase in MMP-2 expression, and inhibition of MCAM using blocking antibodies decreased the expression of MMP-2." (PMID 22272201, 2012). "It suggested that MMP-2 enhance the adhesion of A375 melanoma cells by cleaving fibronectin obviously at 30 min." (PMID 22848537, 2012). "MMP-2 cleaves fibronectin into small fragments to enhance the adhesion and migration of human melanoma cells mediated by αvβ3 integrin." (PMID 22848537, 2012). "We examined the expression of MMP-2 and αvβ3 integrin in human A375 melanoma cells and human M21 melanoma cells using immunofluorescence staining, and demonstrated that MMP-2 accumulated at the leading edge of migrating cells before αvβ3 integrin." (PMID 22848537, 2012). "Several factors involved in melanoma invasion, resistance to apoptosis and proliferation, such as MMP-2, MCAM/MUC18, BCL-2 and TGF-α are regulated by both CREB and AP-2α, albeit in an opposite manner." (PMID 20805990, 2010). "Down-regulation of BRG1 in a highly invasive melanoma cell line resulted in decreased MMP2 expression and decreased invasive ability." (PMID 20969766, 2010). "We showed that recognition of melanoma cells by this CTL clone required MMP-2 secretion and cross-presentation of the HLA-A2-restricted MMP-2560–568 epitope following αvβ3-dependent endocytosis of secreted MMP-2." (PMID 20689590, 2010). "Our data suggested that activation of MMP2 is an important mechanism by which BRG1 promotes melanoma cell invasive ability." (PMID 20969766, 2010). "All these characteristics point to MMP-2 as the target of interest in melanoma immunotherapy protocols." (PMID 20689590, 2010). "Overexpression of MT1-MMP in melanoma cells induced activation of MMP-2 which is crucial for extracellular matrix degradation." (PMID 20631829, 2010). "Specifically, activated Stat3 regulates tumor invasion of melanoma cells by regulating the gene transcription of MMP-2." (PMID 20482858, 2010). "We have previously shown the interaction of MMP-2 with cell surface CD44 in human melanoma cells over expressing OPN." (PMID 17343740, 2007).
melanoma (continued). "We evaluated MMP2 and MMP3 germline polymorphisms in a group of 1002 melanoma patients using PCR-based methods, including fragment size analysis and melting temperature profiles." (PMID 17958893, 2007). "Functional promoter polymorphisms in MMP2 and MMP3 genes were examined in a cohort of 1002 melanoma patients." (PMID 17958893, 2007). "This study does not provide strong evidence for further investigation into the role of the MMP2 and MMP3 variants in melanoma progression." (PMID 17958893, 2007). "In another study, investigators have found strong expression (> 40% cells stained) of MMP2 in 78% of the invasive melanomas." (PMID 17958893, 2007). "It reduced migration and invasion capacity by impairing activation of MMP‐2 in melanoma cells." (PMID 41546170, 2026). "Furthermore, jaceidin reduced the expression of extracellular matrix degradation proteins MMP-2 and cathepsins A. These compelling findings suggest that jaceidin warrants further investigation as a potential therapeutic agent for melanoma." (PMID 41731694, 2026). "MMP-2 plays an important role in the regulation of CAFs infiltration in melanoma." (PMID 40869222, 2025). "Moreover, overexpression of Wnt Family Member 5A (WNT5A) in several melanoma cell lines was associated with increased release of exosomes enriched in VEGF, IL-6, IL-8, and MMP-2." (PMID 39866233, 2025). "Moreover, in melanoma cells, the rapamycin-insensitive companion of mTOR complex 2 (Rictor-mTORC2) can phosphorylate AKT, causing overexpression of MMP-2 and MMP-9 and microvessel formation." (PMID 39866233, 2025). "For example, activation of STAT3 in melanoma could up‐regulate MMP‐2 expression by directly binding to its promoter." (PMID 41425852, 2025). "Our findings demonstrate, for the first time, that five newly synthesized vemurafenib analogs—RF-86A, RF-87A, RF-94A, RF-94B, and RF-96B—effectively reduce the viability of A375 human melanoma cells and inhibit metastatic potential through suppression of MMP-2 and MMP-9 activity." (PMID 40872552, 2025). "Downregulated molecules include MMP2 and N-cadherin, both of which are necessary for melanoma metastasis and invasion, TXNDC5, which increases cell proliferation potential, and UCK2, which enhances melanoma cell migration via the Wnt/β-catenin signaling pathway." (PMID 41157107, 2025). "In melanoma cell lines, the loss of suppressor of cytokine signaling-1 (SOCS-1) expression is correlated with increased STAT3 signaling and subsequent overexpression of MMP-2, basic fibroblast growth factor (bFGF), and VEGF." (PMID 39780275, 2025). "Moreover, B7-H3 influenced EMT processes in glioblastoma, melanoma, and hepatocellular carcinoma by upregulating matrix metalloproteinases MMP-2 and MMP-9 or downregulating E-cadherin levels." (PMID 40801642, 2025). "Moreover, early response biomarkers such as COX-2 and MMP2 can serve as additional tools for improving personalized immunotherapy by predicting patient responses to melanoma immunotherapy." (PMID 39336897, 2024). "Furthermore, DNJ derived from mulberries impeded the proliferation of B16F10 melanoma cells by modulating the activities and expression of matrix metalloproteinase (MMP)-2/9, signifying the anti-metastatic properties against cancerous cells." (PMID 38791372, 2024). "However, in the available literature, its overexpression is related to decreased expression of MMP2, a protein associated with ECM (extracellular matrix) degradation, which consequently reduces the ability of melanoma cells to migrate and invade." (PMID 38601651, 2024). "Similarly, treatment with Terminalia catappa leaf extract suppressed the invasion and migration of melanoma cells and inhibited MMP-2 activity in a concentration-dependent manner." (PMID 39683504, 2024). "Importantly, knocking down CD147 attenuates MMP-2 response to hypoxia in melanoma cell lines, confirming the new mechanism." (PMID 39769454, 2024).